TMOD4 (tropomodulin 4)
Description:
Blocks the elongation and depolymerization of the actin filaments at the pointed end. The Tmod/TM complex contributes to the formation of the short actin protofilament, which in turn defines the geometry of the membrane skeleton.
Synonyms: Sk-Tmod
Tractability: No criterion of Open Targets' tractability assessment is met for any kind of drug.
Gene: Protein-coding gene on chromosome 1 (151,169,984 to 151,176,284, reverse strand). Ensembl gene ENSG00000163157.
Subcellular location: Cytoplasm, cytoskeleton
Pathways (Reactome):
Muscle contraction: Striated Muscle Contraction
Gene Ontology:
Molecular function: protein binding; actin binding; tropomyosin binding
Biological process: actin filament organization; muscle contraction; myofibril assembly; pointed-end actin filament capping
Cellular component: striated muscle thin filament; cytoskeleton
Genetic constraint (gnomAD): Loss-of-function variants: 34 observed, 45.27 expected, observed/expected ratio (o/e) 0.75, 90% interval 0.57 to 1. The upper end of that interval is the gene's LOEUF score, 1, which puts it in group 4 of 6, group 1 being the genes least tolerant of losing a copy. Missense variants: 398 observed, 459.6 expected, observed/expected ratio (o/e) 0.87, 90% interval 0.8 to 0.94. Synonymous variants: 131 observed, 163.35 expected, observed/expected ratio (o/e) 0.8, 90% interval 0.69 to 0.93.
Homologues: Orthologues: chimpanzee TMOD4 (100% identical), macaque TMOD4 (100% identical), pig TMOD4 (98% identical), dog TMOD4 (97% identical), guinea pig TMOD4 (97% identical), mouse Tmod4 (96% identical), rabbit TMOD4 (96% identical), rat Tmod4 (96% identical), tropical clawed frog tmod4 (74% identical), zebrafish tmod4 (67% identical), Caenorhabditis elegans unc-94 (37% identical), Drosophila melanogaster tmod (22% identical). Paralogues in human: TMOD1 (59% identical), TMOD3 (55% identical), TMOD2 (54% identical), LMOD3 (36% identical), LMOD2 (35% identical), LMOD1 (33% identical).
Diseases named in the same sentence as TMOD4 in open-access papers:
TMOD4 is named in the same sentence as 18 diseases in open-access papers, as found by Europe PMC text mining. Sharing a sentence is not in itself a finding about the gene and the disease. The quoted sentences say what the papers report.
nemaline myopathy (2 papers, 2014 to 2023). Nemaline myopathy (NM) encompasses a large spectrum of myopathies characterized by hypotonia, weakness and depressed or absent deep tendon reflexes, with pathologic evidence of nemaline bodies (rods) on muscle biopsy. "The Inactivating biallelic pathogenic sequence variants in the TMOD4 have been associated with myopathy (e.g., nemaline myopathy OMIM #609284) also reported in zebrafish-mutated model, suggesting that TMOD4 mutations may lead to OSAS relevant myopathy, in the intercostal muscles and/or diaphragm." (PMID 37229194, 2023).
atherosclerosis (1 paper, 2025). A disease characterized by the build-up of fatty material and calcium deposition in the arterial wall resulting in partial or complete occlusion of the arterial lumen. "Diseases associated with TMOD4 include atherosclerosis, pulmonary hypertension, and muscle weakness." (PMID 40097750, 2025).
cardiomyopathy (1 paper, 2016). A disease of the heart muscle or myocardium proper. "Accordingly, we identified differential expression in several genes in Idh2R140Q mouse hearts that, when dysregulated, could be implicated in cardiomyopathy, including downregulation of Hopx and Tmod4 and upregulation of Six1 and Nmrk2." (PMID 27469509, 2016).
heart failure (1 paper, 2016). Inability of the heart to pump blood at an adequate rate to meet tissue metabolic requirements. "Several have been shown to be adversely associated with heart failure, namely the transcription factors HOP homeobox (Hopx) and Six homeobox 1 (Six1), the cytoskeletal regulator tropomodulin 4 (Tmod4), and the metabolic gene nicotinamide riboside kinase 2 (Nmrk2)." (PMID 27469509, 2016).
hepatoma (1 paper, 2025). "ELISA results showed that TMOD4 also increased the content of BFSP1 in the supernatant of hepatoma cell culture." (PMID 40097750, 2025).
liver cancer (1 paper, 2025). An epithelial or non-epithelial malignant neoplasm that arises from the liver. "First, although we have confirmed the role of METTL3/BFSP1/TMOD4 axis in the progression and metastasis of liver cancer, since this study is only verified in cell and liver cancer xenograft models, other animal models are needed for further verification." (PMID 40097750, 2025). "In summary, BFSP1 induces aerobic glycolysis and promotes invasion of liver cancer cells by interacting with TMOD4." (PMID 40097750, 2025). "Co-immunoprecipitation (Co-IP) results showed that BFSP1 and TMOD4 were co-precipitated in liver cancer cells." (PMID 40097750, 2025). "The results of transwell showed that overexpression of BFSP1 increased the invasion ability of liver cancer cells by 68%, whereas knockdown of TMOD4 reversed the promotion of overexpression of BFSP1." (PMID 40097750, 2025). "The results showed that TMOD4 was upregulated in tumor tissues of liver cancer patients and liver cancer cell lines." (PMID 40097750, 2025). "The results of XFe24 cell metabolic analysis showed that pcDNA-BFSP1 increased the ECAR level and decreased the OCR level in liver cancer cells, which could be reversed by knockdown of TMOD4." (PMID 40097750, 2025). "On the other hand, whether the BFSP1/TMOD4 axis can be used as a clinical indicator of liver cancer needs to be further verified by expanding clinical samples." (PMID 40097750, 2025). "Similar to the results of our research, we demonstrated that BFSP1 directly interacts with TMOD4 in liver cancer cells, and knockdown of TMOD4 in vitro reversed BFSP1 overexpression-induced aerobic glycolysis and invasion of liver cancer cell." (PMID 40097750, 2025). "In summary, we found that BFSP1 was upregulated in liver cancer, and BFSP1 and its interacting protein TMOD4 work together to affect the viability, invasion, and aerobic glycolysis of liver cancer cells." (PMID 40097750, 2025). "Here, we mainly explored the mechanism of TMOD4 and BFSP1 in liver cancer." (PMID 40097750, 2025). "Co-immunoprecipitation, immunofluorescence and GST pull down analyses showed that BFSP1 directly interacted with tropomodalin 4 (TMOD4), and knockdown of TMOD4 reversed BFSP1 overexpression-induced malignant phenotypes and aerobic glycolysis in liver cancer cells." (PMID 40097750, 2025).
myopathy (3 papers, 2014 to 2025). A disease of the muscle in which the muscle fibers do not function properly. "We therefore suggest that the zebrafish mutant tmod4trg is a novel model for human myopathies, which can be used to study cytoplasmic rod formation, and that TMOD4 is novel candidate gene for unresolved human myopathies." (PMID 25288681, 2014). "The deletion of TMOD4 in murine models does not lead to myopathy." (PMID 40841884, 2025).
tumor (1 paper, 2025). "The results showed that METTL3 overexpression promoted the expression of BFSP1, METTL3, and TMOD4 in mouse tumor tissues, whereas sh-BFSP1 reversed the effect." (PMID 40097750, 2025).
TMOD4 also shares sentences with these, for which no sentence is quoted: cancer (2 papers); malaria (2); male infertility (2); asthenozoospermia (1); cerebral palsy (1); early onset hypertension (1); muscle disorders (1); pancreatic cancer (1); pulmonary hypertension (1); virus infection (1).